Y_RNA (Y RNA )
Gene: Miscellaneous RNA gene on chromosome 4 (159,064,297 to 159,064,398, reverse strand). Ensembl gene ENSG00000206978.
Homologues: Orthologues: chimpanzee Y_RNA (99% identical). Paralogues in human: Y_RNA (86% identical), Y_RNA (84% identical), RNY1P7 (83% identical), Y_RNA (83% identical), RNY1 (82% identical), Y_RNA (82% identical), Y_RNA (81% identical), RNY1P2 (80% identical), Y_RNA (80% identical), Y_RNA (79% identical), RNY1P11 (78% identical), RNY1P8 (78% identical), and 94 more.